ACE (angiotensin I converting enzyme)
Diseases named in the same sentence as ACE in open-access papers (continued):
Sharing a sentence is not in itself a finding about the gene and the disease.
brain disease (1 paper, 2013). "As AD is a brain disease, central ACE inhibitors are expected to be more effective to delay the onset of AD than peripheral ACE inhibitors if a well controlled clinical trial is conducted." (PMID 23948883, 2013).
central nervous system disease (1 paper, 2020). "In the current study, we investigated the serum ACE activity in idiopathic acute ON based on these hypothesis in which ON is considered as an immunologically mediated inflammatory central nervous system disease and ACE activity may be involved in its pathogenesis." (PMID 32318310, 2020).
intestinal disorder (1 paper, 2024). A non-neoplastic or neoplastic disorder that affects the small or large intestine. "Intestinal disorders: The same can be said about the ACE inhibition determined in bread samples when variable pancreatin activity was used during simulated digestion." (PMID 39125365, 2024). "Intestinal disorders: The mostly stable level of ACE inhibition at 100% and 75% pancreatin activity is thought to indicate no clear link between pancreatin and α-amylase activities." (PMID 39125365, 2024).
ACE also shares sentences with these, for which no sentence is quoted: acute myocardial infarction (60 papers); hereditary angioedema (27); peripheral vascular disease (18); transient ischemic attack (17); infectious disease (12); cardiac arrhythmia (11); Duchenne muscular dystrophy (10); idiopathic pulmonary fibrosis (10); orthostatic hypotension (10); toxoplasmosis (10); Hypoalbuminemia (9); acute respiratory failure (8); hypertrophy (8); immune dysfunction (8); inflammatory bowel disease (8); ischemic cardiomyopathy (8); portal hypertension (8); unstable angina (8); alcohol abuse (7); eosinophilia (7); glomerulopathy (7); Lyme disease (7); polycythemia (7); Ventricular hypertrophy (7); ventricular tachycardia (7); AIDS (6); cystic fibrosis (6); hypertriglyceridemia (6); rheumatic heart disease (6); Sjögren syndrome (6).
A further 444 diseases each share a sentence with ACE in 5 papers or fewer.